PLCE1 (phospholipase C epsilon 1)
Description:
The production of the second messenger molecules diacylglycerol (DAG) and inositol 1,4,5-trisphosphate (IP3) is mediated by activated phosphatidylinositol-specific phospholipase C enzymes. PLCE1 is a bifunctional enzyme which also regulates small GTPases of the Ras superfamily through its Ras guanine-exchange factor (RasGEF) activity. As an effector of heterotrimeric and small G protein, it may play a role in cell survival, cell growth, actin organization and T-cell activation. In podocytes, is involved in the regulation of lamellipodia formation. Acts downstream of AVIL to allow ARP2/3 complex assembly.
Synonyms: KIAA1516; PLCE; PPLC; NPHS3
Tractability: Small molecule: a structure with a bound ligand is known. Antibody: its Gene Ontology location is reachable by antibodies, with high confidence; UniProt places it where antibodies can reach, with medium confidence.
Gene: Protein-coding gene on chromosome 10 (93,993,894 to 94,332,823, forward strand). Ensembl gene ENSG00000138193.
Subcellular location: Cytoplasm, cytosol; Cell membrane; Golgi apparatus membrane; Cell projection, lamellipodium; Cytoplasm, perinuclear region
Subcellular location (Human Protein Atlas): Cytosol
Pathways (Reactome):
Metabolism: Synthesis of IP3 and IP4 in the cytosol
Gene Ontology:
Molecular function: enzyme binding; phosphatidylinositol-4,5-bisphosphate phospholipase C activity; phospholipase C activity; protein binding; small GTPase binding; guanyl-nucleotide exchange factor activity; phosphoric diester hydrolase activity
Biological process: diacylglycerol biosynthetic process; epidermal growth factor receptor signaling pathway; glomerulus development; intracellular signal transduction; phospholipase C-activating G protein-coupled receptor signaling pathway; positive regulation of lamellipodium assembly; Ras protein signal transduction; calcium-mediated signaling; G protein-coupled receptor signaling pathway; phosphatidylinositol metabolic process; phosphatidylinositol-mediated signaling; release of sequestered calcium ion into cytosol; lipid metabolic process; signal transduction; small GTPase-mediated signal transduction
Cellular component: cytosol; lamellipodium; plasma membrane; Golgi membrane; perinuclear region of cytoplasm
Genetic constraint (gnomAD): Loss-of-function variants: 110 observed, 228.42 expected, observed/expected ratio (o/e) 0.48, 90% interval 0.41 to 0.56. The upper end of that interval is the gene's LOEUF score, 0.56, which puts it in group 2 of 6, group 1 being the genes least tolerant of losing a copy. Missense variants: 2,343 observed, 2,795 expected, observed/expected ratio (o/e) 0.84, 90% interval 0.81 to 0.87. Synonymous variants: 900 observed, 1,030.2 expected, observed/expected ratio (o/e) 0.87, 90% interval 0.83 to 0.92.
Gene-disease validity (ClinGen):
ClinGen rates the evidence that PLCE1 causes each of these diseases.
nephrotic syndrome, type 3 (autosomal recessive): Definitive. Any nephrotic syndrome in which the cause of the disease is a mutation in the PLCE1 gene.
Homologues: Orthologues: chimpanzee PLCE1 (99% identical), macaque PLCE1 (97% identical), pig PLCE1 (91% identical), dog PLCE1 (90% identical), rabbit PLCE1 (89% identical), guinea pig PLCE1 (87% identical), rat Plce1 (85% identical), mouse Plce1 (85% identical), tropical clawed frog plce1 (67% identical), zebrafish plce1 (57% identical), Caenorhabditis elegans plc-1 (29% identical), Drosophila melanogaster Plc21C (12% identical). Paralogues in human: PLCH1 (14% identical), PLCH2 (14% identical), PLCB1 (13% identical), PLCB4 (13% identical), PLCB2 (13% identical), PLCB3 (13% identical), PLCL2 (13% identical), PLCL1 (12% identical), PLCG2 (12% identical), PLCG1 (11% identical), PLCD4 (11% identical), PLCD1 (11% identical), and 2 more.
Diseases named in the same sentence as PLCE1 in open-access papers:
PLCE1 is named in the same sentence as 107 diseases in open-access papers, as found by Europe PMC text mining. Sharing a sentence is not in itself a finding about the gene and the disease. The quoted sentences say what the papers report.
esophageal cancer (26 papers, 2011 to 2025). A primary or metastatic malignant neoplasm involving the esophagus. "In turn, loss of PLCE1 reduced the invasion and proliferation ability of esophageal cancer cells in vitro and promoted apoptosis in human tongue squamous cell carcinoma." (PMID 40819340, 2025). "Although various studies have shown that genetic variations of PLCE1 are associated with esophageal cancer susceptibility, the functional role of PLCE1 in esophageal cancer had not been evaluated before." (PMID 34912798, 2021). "GWAS found that SNPs in the PLCE1 are mainly rs2274223 A>G and rs3765524 C>T, which are common susceptibility sites for esophageal cancer and gastric cancer." (PMID 34491229, 2021). "The reported risk susceptibility between phospholipase C epsilon 1 (PLCE1) polymorphisms and esophageal cancer (EC) and gastric cancer (GC) remained inconsistent and controversial, especially on variants other than rs2274223." (PMID 30931333, 2019). "For these reasons, many researchers consider PLCE1 gene polymorphisms as one of the significant biomarker involved in esophagus cancer among Chinese populations." (PMID 31649800, 2019). "Previous studies have revealed the risk susceptibility of PLCE1 polymorphism (rs2274223) in esophageal carcinoma, we have also shown that the 5780G allele in PLCE1 is associated with esophagitis and esophageal cancer in high-risk areas of ESCC." (PMID 28402280, 2017). "Our previous study proved that the heterozygote of PLCE1 rs2274223 is associated with the susceptibility to HPV infection in Kazakh patients with esophageal cancer." (PMID 29190930, 2017). "Our previous study showed that phospholipase C elipson 1 (PLCE1) expression is up-regulated and associated with disease progression in esophageal carcinoma." (PMID 29190930, 2017). "PLCE1 overexpression in esophageal cancer cells is caused by multiple factors, including genetic variants of PLCE1, as shown in our previous report, and miRNA regulation, as revealed in the present study." (PMID 26657507, 2016). "We also confirmed that the heterozygote of PLCE1 rs2274223 increase susceptibility to HPV infection in Kazakh patients with esophageal carcinoma." (PMID 26657507, 2016). "This study analyzed the expression levels of and correlation between PLCE1 and PRKCA in human esophagitis, carcinogen NMBA-induced rat esophagus, PLCE1 genetic deficient mouse esophageal epithelial tissues and human esophageal cancer cell line, integrated with Online oncology data sets." (PMID 28402280, 2017). "However, PRKCA and cytokines were significantly downregulated in PLCE1-deficient mouse esophageal epithelia, and knockdown of PLCE1 in human esophageal cancer cells led to reduction of PRKCA and cytokines." (PMID 28402280, 2017). "Moreover, the heterozygote of PLCE1 rs2274223 increases susceptibility to HPV infection in Kazakh patients with esophageal carcinoma." (PMID 26657507, 2016). "miR-145 achieves this inhibitory effect by suppressing the translation of PLCE1, ultimately curbing the proliferation, migration, and metastasis of esophageal cancer cells." (PMID 37842637, 2023). "Hypomethylated PLCE1 stimulates esophageal carcinoma angiogenesis and proliferation by activating the PI-PLC epsilon-NF-B signaling pathway and VEGF-C/Bcl-2 expression." (PMID 35765945, 2022). "In esophageal cancer, the up-regulation of PLCE1 oncoprotein through epigenetic mechanisms drives esophageal cancer angiogenesis and proliferation by activating the NF-κB signaling pathway." (PMID 34722553, 2021). "Targeting oncogenic PLCE1 by miR-145 can impair tumor proliferation and metastasis of esophageal cancer." (PMID 30609930, 2019). "The expression level of PLCE1 in GSE9982 esophageal cancer cell lines suggests high expression of PLCE1 in cancer cell lines (P = 0.0009)." (PMID 30609930, 2019).
esophageal cancer (continued). "As an angiogenic switch, PLCE1-mediated activation of NF-κB /VEGF-C signaling is involved in the angiogenesis of esophageal cancer, which not only supplies nutrients and oxygen to proliferative tumor cells, but also serves as the conduit for migration." (PMID 30609930, 2019). "Recent studies suggested that PLCE1 expression is regulated by miRNAs in esophageal cancer, and miRNAs regulating PLCE1 are involved in numerous cellular biological behaviors, including cell proliferation, apoptosis, and migration." (PMID 29190930, 2017). "Several genes/pathways have been implicated to esophageal cancer migration, such as Cdc42, HGF/SF, Androgen receptor, RhoA, Rac-1, and Cdc42, VEGF, HER2, PLCE1, ABCG2/V-ATPase, MMS19." (PMID 28147311, 2017). "We comprehensively demonstrated the suppressive role of miR-145 on PLCE1 expression and esophageal cancer cell proliferation and invasion." (PMID 26657507, 2016). "In the present study, PLCE1 knockdown reduced cell growth/proliferation and increased the frequency of apoptotic esophageal cancer cells." (PMID 26657507, 2016). "The present study provides the first evidence that miR-145 inhibits proliferation and invasion of esophageal cancer by binding directly to the 3′-UTR of PLCE1." (PMID 26657507, 2016). "As such, in the present study, we comprehensively investigated the function of PLCE1 in esophageal cancer." (PMID 26657507, 2016). "Molecular pathways leading to PLCE1 overexpression are potentially important oncogenic mechanisms for esophageal cancer development." (PMID 26657507, 2016). "Co-transfection of PLCE1 siRNA with miR-145 mimic into the Eca109 esophageal cancer cells revealed that the transfection attenuated the elevated PLCE1 expression." (PMID 26657507, 2016). "In the current meta-analysis, we ascertained that the PLCE1 rs2274223 A>G polymorphism was significantly associated with increased DTC risk, especially with gastric cancer and esophageal cancer." (PMID 24116107, 2013). "In conclusion, our meta-analysis suggests that the PLCE1 rs2274223 A>G polymorphism is associated with DTC risk, especially with gastric cancer and esophageal cancer." (PMID 24116107, 2013). "In esophageal cancer, miR-328 suppresses cell survival by targeting PLCE1." (PMID 31492116, 2019). "Overall, the induction of PLCE1 degradation by hypermethylation may be a therapeutic strategy for preventing PLCE1 activity and treating esophageal cancer." (PMID 30609930, 2019). "miR-328 suppresses the survival of cancer cells by targeting PLCE1 in esophageal cancer, inhibits epithelial to-mesenchymal transition in renal tubular cells by targeting CD44, and regulates cell invasion and proliferation in glioma cells by targeting SFRP1 and in melanoma cells by targeting TGFb2." (PMID 29374351, 2018). "Finally, high expression of both PLCE1 and PRKCA is significantly associated with poor outcomes of the patients with esophageal cancers." (PMID 28402280, 2017). "Enhanced PLCE1 expression contributed to aggressive esophageal cancer growth and migration." (PMID 26657507, 2016). "Hence, delivery of PLCE1-targeting miR-145 is a potential therapeutic approach for esophageal cancer." (PMID 26657507, 2016). "Thus, the present mechanistic study indicates that delivery of PLCE1-targeting miR-145 is a candidate therapeutic approach for preventing tumor proliferation and metastasis of esophageal cancer." (PMID 26657507, 2016). "To determine whether miRNAs upregulate PLCE1 expression in esophageal cancer, we determined miRNAs targeting PLCE1 by using online miRNA target prediction databases (TargetScan, miRanda, and miRDB)." (PMID 26657507, 2016).
esophageal cancer (continued). "Furthermore, Pearson correlation showed a significant inverse correlation between miR-145 and PLCE1 protein expression in esophageal carcinoma tissues from the Chinese Han ethnic group (R = −0.472, **P = 0.008)." (PMID 26657507, 2016). "This study has also strongly suggested that the co-expression of PLCE1 and PRKCA could be an indicator for predicting of esophageal cancer patient outcomes, and the partnership of PLCE1 and PRKCA could be a therapeutic target instead of a single target for personalized therapy or prevention." (PMID 28402280, 2017). "However, targeting PLCE1 may be one mechanism through which miR-145 exerts its tumor-suppressive function in esophageal cancer." (PMID 26657507, 2016). "Thus, PLCE1 is likely to become a focus of esophageal cancer treatment." (PMID 26657507, 2016). "The expression of EMT markers, namely, the epithelial cell marker E-cadherin and the mesenchymal marker vimentin, in si-PLCE1-transfected Eca109 and EC9706 cells and in the controls were examined using Western blot analysis to investigate whether PLCE1 promotes EMT in esophageal cancer cells." (PMID 26657507, 2016). "With the advances in the management of gastrointestinal cancers, the combination of PLCE1 and PRKCA could be an immune checkpoint for esophageal cancer therapy." (PMID 28402280, 2017). "PLCE1 expression levels serve as potential biomarkers of ESCC, and delivery of PLCE1-targeting miR-145 is a candidate therapeutic approach for preventing tumor proliferation and metastasis of esophageal cancer." (PMID 26657507, 2016). "In addition, increased PLCE1 expression levels influence ESCC cell proliferation, as well as esophageal carcinoma cell migration and invasion." (PMID 26657507, 2016). "However, the mechanisms contributing to PLCE1 overexpression in esophageal cancers have not been reported yet." (PMID 26657507, 2016). "We previously reported that PLCE1 protein expression is upregulated in Kazakh patients with ESCC; we also confirmed that this protein functions as an oncogene and can induce inflammation and promote esophageal cancer formation through interaction with the NF-κB signal pathway." (PMID 26657507, 2016). "Similarly, the present findings confirmed that PLCE1 controlled cytoskeleton dynamics by increasing F-actin expression, an indicator of cytoskeleton dynamics, and by promoting the EMT of esophageal cancer cells, thereby altering esophageal cellular shape, motility, and migration." (PMID 26657507, 2016). "However, whether the expression of PLCE1 and PRKC is associated with esophageal inflammation and progression to esophageal cancer is not clear." (PMID 28402280, 2017).
esophageal squamous cell carcinoma (20 papers, 2011 to 2025). Esophageal squamous cell carcinoma (ESCC) is a type of esophageal carcinoma (EC) that can affect any part of the esophagus, but is usually located in the upper or middle third. "Multiple mutations at the 10q23 locus in PLCE1 are associated with the high incidence of gastric and esophageal squamous cell carcinoma." (PMID 35765945, 2022). "The genetic variant PLCE1 rs2274223 is significantly related to cardia cancer, and rs17417407 is related to the incidence of esophageal squamous cell carcinoma in humans." (PMID 35765945, 2022). "As a susceptible gene for GCa and esophageal squamous cell carcinoma, the effect of PLCE1 in tumorigenesis was also elucidated by a recent study, in which the PLCE1 gene targeted by miR-145 impaired tumor metastasis and proliferation." (PMID 27821817, 2017). "Phospholipase C epsilon 1 (PLCE1) is a susceptibility gene in esophageal squamous cell carcinoma (ESCC)." (PMID 26657507, 2016). "Two recent genome-wide association studies have identified a shared susceptibility variation PLCE1 rs2274223 for esophageal squamous cell carcinoma (ESCC) and gastric cardia adenocarcinomas (GCA)." (PMID 23874915, 2013). "In esophageal squamous cell carcinoma (ESCC), PLCE1 expression was upregulated and associated with poor overall survival and resistance to chemotherapy." (PMID 34412652, 2021). "For example, the oncoprotein PLCE1 of esophageal squamous cell carcinoma (ESCC) was observed to promote the growth and proliferation of tumor blood vessels by upregulating VEGF-C." (PMID 34504884, 2021). "Hypomethylation-induced PLCE1 in esophageal squamous cell carcinoma (ESCC) cohorts can bind and phosphorylate p65 and IκBα proteins." (PMID 34722553, 2021). "Rs2274223 A>G has been linked to altered PLCE1 expression in esophageal squamous cell carcinoma(ESCC), and the G allele may contribute to increased cancer incidence." (PMID 28418898, 2017). "A single nucleotide polymorphism (SNP, rs2274223) in PLCE1 has been identified as a novel susceptibility locus in genome-wide association studies (GWAS) of esophageal squamous cell carcinoma (ESCC) and gastric cardia adenocarcinoma (GCA) that share similar risk factors with SCCHN." (PMID 21689432, 2011). "MiR-145 could inhibit cell invasion and migration by targeting TWIST in Colorectal Cancer, TGFBR2/Smad3 axis in bladder cancer, phospholipase C epsilon 1 in esophageal squamous cell carcinoma, ADAM19 in glioblastoma, and TGF-β1 in breast cancer." (PMID 32083506, 2020). "PLCE1 positively regulates esophageal squamous cell carcinoma (ESCC) migration and invasion." (PMID 40266671, 2025). "A study in esophageal squamous cell carcinoma showed that inflammation or immune-related TLR4, IL-8, IL-6, and chemokine (C-X-C motif) ligand 2 (CXCL2) were increased upon PLCE1 suppression." (PMID 35054579, 2021). "Phospholipase C epsilon 1 (PLCE1), has been found to promote angiogenesis and proliferation in esophageal squamous cell carcinoma by activating the NF-κB signaling pathway and inducing VEGF-C/Bcl-2 expression." (PMID 34193202, 2021). "We found that the expression levels of both PLCE1 and PRKCA were significantly elevated in human esophagitis, esophageal squamous cell carcinoma, Barrett's esophagus, esophageal adenocarcinoma and in NMBA-treated rat esophageal epithelia." (PMID 28402280, 2017).